Y_RNA (Y RNA )
Gene: Miscellaneous RNA gene on chromosome 12 (17,710,934 to 17,711,046, forward strand). Ensembl gene ENSG00000206662.
Homologues: Orthologues: chimpanzee Y_RNA (99% identical), macaque Y_RNA (93% identical). Paralogues in human: RNY1 (81% identical), RNY1P8 (78% identical), Y_RNA (78% identical), Y_RNA (77% identical), Y_RNA (76% identical), RNY1P11 (75% identical), RNY1P12 (75% identical), Y_RNA (75% identical), Y_RNA (74% identical), RNY1P10 (73% identical), RNY1P7 (73% identical), Y_RNA (73% identical), and 87 more.